SLC9D1 (solute carrier family 9 member D1)
Description:
Probable Na(+):H(+) or K(+):H(+) antiporter (Probable). Upon IGF1-dependent phosphorylation, facilitates the membrane translocation and activation of AKT1.
Synonyms: C13orf11; TMCO3; FLJ20623
Tractability: Antibody: UniProt predicts a signal peptide or a membrane-spanning region. PROTAC: ubiquitination databases record sites on it; its protein half-life has been measured.
Gene: Protein-coding gene on chromosome 13 (113,490,816 to 113,554,590, forward strand). Ensembl gene ENSG00000150403.
Subcellular location: Golgi apparatus membrane; Cell membrane
Subcellular location (Human Protein Atlas): Cytosol
Gene Ontology:
Molecular function: protein-membrane adaptor activity; antiporter activity; potassium:proton antiporter activity
Biological process: positive regulation of phosphatidylinositol 3-kinase/protein kinase B signal transduction; monoatomic cation transport; potassium ion transmembrane transport; proton transmembrane transport; transmembrane transport
Cellular component: Golgi membrane; plasma membrane; membrane
Genetic constraint (gnomAD): Loss-of-function variants: 45 observed, 54.65 expected, observed/expected ratio (o/e) 0.82, 90% interval 0.65 to 1.06. The upper end of that interval is the gene's LOEUF score, 1.06, which puts it in group 4 of 6, group 1 being the genes least tolerant of losing a copy. Missense variants: 757 observed, 809.87 expected, observed/expected ratio (o/e) 0.93, 90% interval 0.88 to 0.99. Synonymous variants: 362 observed, 336.55 expected, observed/expected ratio (o/e) 1.08, 90% interval 0.99 to 1.17.
Homologues: Orthologues: mouse Tmco3 (90% identical), guinea pig TMCO3 (89% identical), rat Tmco3 (89% identical), dog TMCO3 (88% identical), macaque TMCO3 (84% identical), chimpanzee TMCO3 (84% identical), rabbit TMCO3 (83% identical), pig TMCO3 (82% identical), tropical clawed frog tmco3 (81% identical), zebrafish tmco3 (67% identical).
Diseases named in the same sentence as SLC9D1 in open-access papers:
SLC9D1 is named in the same sentence as 6 diseases in open-access papers, as found by Europe PMC text mining. Sharing a sentence is not in itself a finding about the gene and the disease.
SLC9D1 shares sentences with these, for which no sentence is quoted: tumor (7 papers); cancer (4); hepatocellular carcinoma (2); neuroblastoma (2); cataract (1); Sepsis (1).